SNORD115-41 (small nucleolar RNA, C/D box 115-41)
Synonyms: HBII-52-41
Gene: Small nucleolar RNA gene on chromosome 15 (25,245,478 to 25,245,559, forward strand). Ensembl gene ENSG00000200478.
Gene Ontology:
Biological process: RNA processing
Cellular component: nucleolus
Homologues: Orthologues: chimpanzee SNORD115 (99% identical). Paralogues in human: SNORD115-26 (99% identical), SNORD115-11 (98% identical), SNORD115-29 (98% identical), SNORD115-36 (98% identical), SNORD115-43 (98% identical), SNORD115-12 (96% identical), SNORD115-16 (96% identical), SNORD115-22 (96% identical), SNORD115-31 (96% identical), SNORD115-39 (96% identical), SNORD115-44 (96% identical), SNORD115-6 (96% identical), and 37 more.